LYZ (lysozyme)
Diseases named in the same sentence as LYZ in open-access papers (continued):
Sharing a sentence is not in itself a finding about the gene and the disease.
dacryoadenitis (1 paper, 2025). Inflammation and enlargement of the lacrimal gland. "Of the 14 patients diagnosed with dacryoadenitis, ACE was positive in 2 of 13 (15.3%) patients tested, lysozyme in 1 of 12 (8.3%) patients tested, SS-A in 1 of 5 (20%) patients tested, and C-ANCA 1 of 10 (10%) patients tested." (PMID 40475267, 2025).
dendritic cell neoplasms (1 paper, 2024). "The 5th edition of the WHO Classification of Hematolymphoid Tumors subcategorizes the dendritic cell neoplasms under the spectrum of histiocytic/dendritic cell neoplasms based on their histogenesis and their distinct immunophenotypic profile (positive for CD45, CD4, CD68, CD163, and lysozyme)." (PMID 39592527, 2024).
dysplasia (1 paper, 2024). A usually neoplastic transformation of the cell, associated with altered architectural tissue patterns. "Further analysis of LYZ gene expression showed a significant increase in normal tissue of patients with IBD only, compared to any tissue type from patients who also had dysplasia/CAC, and inflamed tissue from IBD patients, when examining full ROIs." (PMID 38505585, 2024). "The LYZ gene, coding for lysozyme, was significantly decreased in CD3-positive morphology regions of all types of tissue in IBD patients with dysplasia/CAC (progressors), compared to those without dysplasia/CAC." (PMID 38505585, 2024). "Analysis of expression by morphology region showed a decreased/absent expression of LYZ in CD3 and CD45-positive cells from patients with dysplasia/CRC in contrast to the significant elevation of expression in tissue from patients with IBD alone (logFC = 1.6; P = 0.001)." (PMID 38505585, 2024).
eating disorder (1 paper, 2021). A broad group of psychological disorders with abnormal eating behaviors leading to physiological effects from overeating or insufficient food intake. "This study proved that the addition of L. plantarum, L. rhamnosus and C. butyricum reversed the decrease in serum lysozyme and IgM content caused by pellet-feed feeding, which may further ameliorate eating disorders by regulating the appetite and gut microbiota of mandarin fish." (PMID 34204793, 2021).
eccrine carcinoma (1 paper, 2015). An adenocarcinoma with eccrine differentiation arising from the sweat glands. "A number of other reports have indicated that staining for CD15 and lysozyme may help distinguish between PASGC and eccrine carcinoma and that androgen receptor positivity is strongly associated with PASGC carcinoma." (PMID 25888740, 2015).
egg allergy (1 paper, 2023). A food allergy that is an allergy or hypersensitivity to dietary substances from the yolk or whites of eggs, causing an overreaction of the immune system which may lead to severe physical symptoms. "However, high in vitro baseline IL-5 responses to lysozyme and IL-13 responses to both ovalbumin and lysozyme were associated with IgE-mediated hen’s egg allergy at 12 months of age." (PMID 36756279, 2023).
endometritis (1 paper, 2015). An acute or chronic, usually bacterial infectious process affecting the endometrium. "This correlation with induced endometritis has previously been described for lysozyme in response to an intrauterine infusion of Sc. zooepidemicus." (PMID 26572250, 2015).
endothelial dysfunction (1 paper, 2016). In vascular diseases, endothelial dysfunction is a systemic pathological state of the endothelium (the inner lining of blood vessels) and can be broadly defined as an imbalance between vasodilating and vasoconstricting substances produced by (or acting on) the endothelium. "Administration of a lysozyme hydrolysate with alcalase did not modify body weight, nor improved the metabolic parameters of obese diabetic Zucker rats, but it exerted beneficial effects on renal damage and endothelial dysfunction, at least partially through a decreasing effect on oxidative stress." (PMID 26985993, 2016).
essential thrombocythemia (1 paper, 2021). A chronic myeloproliferative neoplasm that involves primarily the megakaryocytic lineage. "In addition, LYZ could interact with CD34+ cells and neutrophils, which may predict an increased risk of thrombosis in essential thrombocythemia patients." (PMID 33587010, 2021).
eyelid tumors (1 paper, 2015). "The results revealed significant differences in lysozyme concentration between patients with or without eyelid tumors in the DE group (p = 0.004)." (PMID 25914748, 2015). "The concentrations of lysozyme were lower in the presence of eyelid tumors in the DE group, compared to the patients without eyelid tumors from the same group." (PMID 25914748, 2015). "Also, it was noticed that there were lower concentrations for lysozyme in the DE group, compared to NDE group in the presence of eyelid tumors." (PMID 25914748, 2015). "Tear lysozyme, lactoferrin and lipocalin concentrations were determined via electrophoresis and the results for patients with or without eyelid tumors were compared." (PMID 25914748, 2015). "Also, it was observed that there were lower concentrations for lysozyme in the group with DE, compared with the NDE group in the presence of eyelid tumors." (PMID 25914748, 2015). "The concentrations of the three tear biomarkers analyzed (lactoferrin, lysozyme and lipocalin) were examined and some differences between the patients with and without eyelid tumors regarding the presence of DE were discovered." (PMID 25914748, 2015). "The analysis of variance (ANOVA) showed that there is a statistically significant difference between the presence/ absence of eyelid tumors in the DE group for lysozyme (p=0.004)." (PMID 25914748, 2015). "Thus, it was observed that there was a statistically significant difference between the presence/ absence of eyelid tumors in the DE group for lysozyme (p=0.004)." (PMID 25914748, 2015). "Thus, the hypothesis was that there was a correlation between DE and eyelid tumors through the activity of MMP and the assumption that the levels of lysozyme and lactoferrin were launched and are related to the activity of MMP." (PMID 25914748, 2015). "Thus, the concentrations of lysozyme were lower in the presence of eyelid tumors in the DE group, compared to the patients without eyelid tumors from the same group." (PMID 25914748, 2015).
fatty liver (1 paper, 2022). "The MS-275 improved hepatic metabolic alterations in HFD-induced fatty liver by increasing the dynamic degradation of hepatic LDs and the interaction between LDs and lysozyme in the fatty liver." (PMID 36077368, 2022).
fish disease (1 paper, 2023). Diseases of freshwater, marine, hatchery or aquarium fish. "On the other hand, immunostimulants and dietary supplements like prebiotics are associated with increasing lysozyme levels and fish complement titer, conferring protection against various fish diseases." (PMID 38138020, 2023).
follicular lymphoma (1 paper, 2025). Follicular lymphoma is a form of non-Hodgkin lymphoma characterized by a proliferation of B cells whose nodular structure of follicular architecture is preserved. "Notably, LYZ displayed a pronounced association specifically with follicular lymphoma but was also observed in non‐follicular lymphoma." (PMID 40360443, 2025).
food allergy (1 paper, 2015). Gastrointestinal disturbances, skin eruptions, or shock due to allergic reactions to allergens in food. "However, it is difficult to determine the true prevalence of food allergy involving lysozyme." (PMID 26197307, 2015). "Being an egg allergen (see Section 3.1.1.), the critical point is again the safety of wines treated with lysozyme for subjects suffering from food allergy, since the additive remains in final wine, if it is not removed by a secondary specific treatment." (PMID 26197307, 2015).
glomerulonephritis (1 paper, 2025). A renal disorder characterized by damage in the glomeruli. "Glomerulonephritis samples additionally showed expression of collagen (COL1A1) and immune cell markers for monocytes or macrophages (LYZ and CD163) and T cells (CD3D, CD3E and CD3G)." (PMID 41028563, 2025).
gram-negative bacterial infections (1 paper, 2015). Infections caused by bacteria that show up as pink (negative) when treated by the gram-staining method. "In P. xylostella, gloverin and lysozyme may mainly function in defense against Gram-positive bacteria, while cecropin and moricin may mainly defend against Gram-negative bacterial infection." (PMID 25943446, 2015).
Graves' orbitopathy (1 paper, 2023). "LYZ can be used as a new biomarker in diseases such as acute intracerebral hemorrhage and Graves' orbitopathy." (PMID 37716978, 2023).
HIV-1 infection (1 paper, 2018). The type species of lentivirus and the etiologic agent of acquired immunodeficiency syndrome (AIDS). "For example, human lysozyme has been shown to inhibit HIV-1 infection in vitro by preventing the adsorption and penetration of the virus." (PMID 30256850, 2018).
iron deficiency (1 paper, 2017). "There is a general agreement that the key processes in egg white defense are iron deficiency (through iron chelation by ovotransferrin) and disruption of bacterial membranes by antimicrobial compounds (lysozyme, ovotransferrin, and various other antimicrobial molecules)." (PMID 28553268, 2017).
latent syphilis (1 paper, 2016). A stage of syphilis characterized by the serologic evidence of infection by Treponema pallidum without evidence of accompanying signs or symptoms related to the disease. "However, elevated serum lysozyme levels might be also detected in ocular involvement of infectious diseases such as presumed latent TB and presumed latent syphilis." (PMID 26879979, 2016). "However, elevated serum lysozyme level might be also detected in ocular involvement of infectious diseases such as presumed latent tuberculosis and presumed latent syphilis." (PMID 26879979, 2016). "Our study disclosed that increase in serum lysozyme levels is more significant than increase in serum ACE levels for patients with infectious uveitis such as presumed latent TB and presumed latent syphilis." (PMID 26879979, 2016).
leprosy (1 paper, 2020). Leprosy is a chronic infectious disease affecting primarily the skin and peripheral nervous system. "The other, meanwhile, was observed primarily in a single leprosy patient and was defined by genes involved in extracellular proteolysis (LYZ, CHIT1, and CHI3L1)." (PMID 33053333, 2020).
Lymphadenopathy (1 paper, 2023). Enlargement (swelling) of a lymph node. "A chest CT scan showed lymphadenopathy in his bilateral hilar regions and a granular shadow in his right lung despite no elevation of serum angiotensin-converting enzyme (ACE) or lysozyme." (PMID 38005993, 2023).
lymphocytic colitis (1 paper, 2014). Microscopic colitis characterized by the accumulation of lymphocytes in the colonic epithelium and lamina propria. "In lymphocytic colitis, lysozyme is up-regulated in macrophages underlying the surface epithelium of the lamina propria, as well as in the lower part of the crypts." (PMID 25437608, 2014).
lysosomal disorders (1 paper, 2012). "Future studies will also focus on determining whether lysozyme and other lysosomal/secretory proteins are disease markers in human NPC patients as well as other lysosomal disorders." (PMID 23094108, 2012).
male infertility (1 paper, 2021). The inability of the male to effect fertilization of an ovum after a specified period of unprotected intercourse. "Thus, recent studies described that LYZ is present in the sperm cell surface and that its neutralization in male rats induces male infertility, by impairing acrosome reaction." (PMID 33898456, 2021).
measles (1 paper, 2019). A highly contagious viral infection caused by the measles virus. "Additionally, we observed increased sinus histiocytosis (Iba1-, CD68-, and lysozyme-expressing cells) in these dolphins, recapitulating features observed in acute/subacute measles and distemper." (PMID 30936878, 2019).
myeloid leukemia (1 paper, 2013). A clonal proliferation of myeloid cells and their precursors in the bone marrow, peripheral blood, and spleen. "Occasionally, myeloid leukemia can firstly present in skin, in which CD68 and lysozyme positivity could be observed and sometimes difficult to be distinguished from LCS." (PMID 23388086, 2013).
myeloid sarcoma (1 paper, 2021). A tumor mass composed of myeloblasts or immature myeloid cells. "CD34, MPO, CD117, CD68, and lysozyme positivity also support the diagnosis of myeloid sarcoma." (PMID 33432557, 2021).
myocarditis (1 paper, 2023). Myocarditis is a condition that is characterized by inflammation of the heart muscle (myocardium). "To examine the role of macrophage CAR expression in the pathogenesis of myocarditis, we generated mice with CAR KO using the Cre-LoxP recombination system with the murine lysozyme promoter Cre." (PMID 36982385, 2023).
nephrotic syndrome (1 paper, 2020). A collection of symptoms that include severe edema, proteinuria, and hypoalbuminemia; it is indicative of renal dysfunction. "The possible mechanisms are monocytosis, increased serum and urine lysozyme levels and tumor necrosis factor-alpha (TNF-α) in MDS patients related to nephrotic syndrome or interstitial nephritis." (PMID 32968161, 2020).
NK/T-cell lymphoma (1 paper, 2019). "Examples include nasal-type extranodal NK/T-cell lymphoma which, unlike BPDCN, will express for Epstein-Barr virus–encoded small RNAs by in situ hybridization, or cutaneous monocytic leukemias, which will express lysozyme." (PMID 31246550, 2019).
obstructive sleep apnea syndrome (1 paper, 2025). Cessation of air flow during sleep due to upper airway obstruction. "This study investigates the link between tear lactoferrin, lysozyme, albumin levels and obstructive sleep apnea syndrome." (PMID 40547925, 2025).
ocular infection (1 paper, 2025). "This study also assessed the translational potential of combination strategy in skin and ocular infection models (both were mucosal indications) by combining TP with lysozyme as the representative combination." (PMID 40912150, 2025). "Considering that lysozyme is a self-secreted macro-molecular cellular metabolite in tears, we next assessed the potential of combination therapy using an ocular infection model." (PMID 40912150, 2025).
otitis (1 paper, 2021). "The otitis-simulating solution was prepared following typical concentration of salts, glucose, albumin, and lysozyme found in serous middle ear effusions (SMEE) of patients with COM with effusion, which is inflammation driven." (PMID 34575515, 2021).
parasitic infections (1 paper, 2023). "Lysozyme is an important indicator of the non-specific immune response, the activity of which might be increased in fish against bacterial, viral and parasitic infections." (PMID 37627421, 2023).
pericardial effusion (1 paper, 2024). Fluid collection within the pericardial sac, usually due to inflammation. "In this regard, a study found that measuring lysozyme levels in fluids, including pericardial effusions, can help distinguish between tuberculous and non-tuberculous effusions in children." (PMID 38392848, 2024).
Pleural effusion (1 paper, 2026). The presence of an excessive amount of fluid in the pleural cavity. "Pleural fluid lysozyme was evaluated as a diagnostic biomarker to differentiate tubercular from non-tubercular pleural effusions." (PMID 42226837, 2026). "Pleural fluid lysozyme may serve as a useful adjunct biomarker in differentiating tubercular from non-tubercular pleural effusions." (PMID 42226837, 2026).
Pseudomonas infection (1 paper, 2024). Infections with bacteria of the genus pseudomonas. "Water irrigation for cerumen removal increases susceptibility to Pseudomonas infection in elderly diabetics by lowering ear wax acidity and lysozyme levels." (PMID 39171050, 2024).
rheumatic diseases (1 paper, 2022). "Klockars indicated that patients with rheumatoid disease had significantly higher levels of lysozyme in synovial fluid than patients with non-rheumatic diseases." (PMID 35359923, 2022).
Rotavirus infection (1 paper, 2013). Infection with any of the rotaviruses. "Furthermore, immunostaining showed that lysozyme was increased in ilea from HRV and LGG+HRV pigs compared with mock and LGG only pigs, which was consistent with the real-time PCR result that rotavirus infection induced high levels of lysozyme mRNA (data not shown)." (PMID 23924832, 2013).
salivary gland inflammation (1 paper, 2023). "It is possible that lysozyme in sialoliths does not originate from saliva but from neutrophil infiltration as a result of recurrent subclinical salivary gland inflammation due to the sialolith." (PMID 36396778, 2023).
sarcoma (1 paper, 2018). A usually aggressive malignant neoplasm of the soft tissue or bone. "Histiocytic sarcoma cells are derived from bone marrow monocyte precursors, expresses monocyte-macrophage antigens (CD163, CD68, and lysozyme) and lack expression of myeloid antigens such as CD33, CD13 and MPO." (PMID 29463311, 2018).
sarcopenia (1 paper, 2026). Progressive decline in muscle mass due to aging which results in decreased functional capacity of muscles. "We identified seven robust protein signatures (LRG1, CST3, TIMP1, C2, ITIH1, AMBP and LYZ) that showed consistent significant associations with sarcopenia components in both cohorts." (PMID 41782349, 2026).
schizophrenia (1 paper, 2020). A major psychotic disorder characterized by abnormalities in the perception or expression of reality. "Analysis of substrate specificity demonstrated that the IgGs of two different schizophrenia patients effectively hydrolyzed five histones and MBP, but did not hydrolyze other control proteins (human and bovine serum albumin, human milk lactoferrin, human lysozyme) under the same reaction conditions." (PMID 33008051, 2020).
serous carcinoma (1 paper, 2024). "S-100 and EMA positivity are the main markers for distinguishing AcCC from serous carcinoma; typical breast AcCC shows acinar cell differentiation and lysozyme-positive cytoplasm rich in enzyme-producing granules, which are positive to the special staining PAS and PAS-D." (PMID 40051607, 2024).
sleep disorder (1 paper, 2023). A change from the patient's baseline sleeping pattern, in the hours slept and/or an alteration/dysfunction in the stages of sleep. "In a similar manner, puerarin was observed to exert the same modulatory effect on colonic inflammation and intestinal stem cells under conditions of sleep disorders, including an increase in lysozyme levels and a promotion of intestinal stem cell proliferation." (PMID 37698689, 2023).
steatosis (1 paper, 2021). Increased lipid within the cytoplasm of cells. "The fish fed 12.5IM diet reduced enterocyte steatosis in pyloric caeca, improved distal intestine histology, had a higher plasma lysozyme content compared to 6.25IM, and tend to increase phagocytic activity in head-kidney macrophages-like cells." (PMID 33717079, 2021). "The fish fed 12.5IM diet reduced enterocyte steatosis in PC, improved DI histology, had a higher plasma lysozyme activity compared to 6.25IM, and tend to increase phagocytic activity in HK macrophages-like cells against P. salmonis." (PMID 33717079, 2021).
Streptococcus pneumonia (1 paper, 2017). "As recently reported, NOD2 recognizes lysozyme-digested PGN processed by professional phagocytes and releases chemokine MCP-1/CCL2 to recruit additional monocytes/macrophages to restrict/clear Streptococcus pneumonia colonization in mice." (PMID 28165033, 2017).
T-cell lymphomas (1 paper, 2015). "Since MS may express T-cell markers (such as CD43, CD45, CD4, and CD7), immunohistochemical expressions of MPO, lysozyme, and CD68 should be analyzed for their distinction from T-cell lymphomas." (PMID 25805673, 2015).
trachoma (1 paper, 2023). "We then investigated these relationships in a Tanzanian cohort study, and tested whether tear lysozyme and lactoferrin are differentially regulated in trachoma." (PMID 37862368, 2023).